FAP (fibroblast activation protein alpha)
Diseases named in the same sentence as FAP in open-access papers (continued):
Sharing a sentence is not in itself a finding about the gene and the disease.
tumor (continued). "Although aPSCs in the present study were cultured in a separate microchannel to interact with tumor cells only via soluble factors, a myofibroblastic phenotype was evident, characterized by 2 to 5-fold higher expression of α-SMA and FAP-α compared to naïve PSCs (data not shown)." (PMID 37759302, 2023). "In contrast, FAP(mF3) UCAR T cells also failed to sensitize these tumors to Meso UCAR T-cell cytotoxicity in vivo, in agreement with their inability to deplete CAFs or increase CD8+ T-cell infiltration in the tumor stroma." (PMID 37251405, 2023). "In addition, the mRNA levels of CDK1 showed significant positive correlations with FGF20 in FAP(+) CAFs and FGFR2 in PanCK(+) tumor epithelial cells at EOCC tumor invasive margin, but not at LOCC tumor invasive margin." (PMID 37964075, 2023). "Compared to other tumor targets that are vastly used in nuclear medicine such as prostate-specific membrane antigen (PSMA) or somatostatin receptor (SSTR), radiopharmaceuticals targeting FAP do not address the cancer cells directly but indirectly via its TME." (PMID 36980775, 2023). "Peritoneal CAFs were isolated from tumor-bearing WT or TgMISIIR-TAg-Low mice by negative selection using the CD45+ column, and recovered cells consisting of over 88% of CD49e+ FAP+ CAFs were injected i.p. into WT mice 1 day after tumor inoculation, followed by OV-CXCR4-A treatment 9 days later." (PMID 36875325, 2023). "Furthermore, the transplantation route did not influence the expression of α-SMA, SPARC and FAP, but we found a higher ratio of collagen I in orthotopic PDX models and a decrease in corresponding tumor cells." (PMID 38136299, 2023). "In contrast, we found that FAP and PDPN were specifically expressed in fibroblasts in tumor tissues but almost absent in normal tissues, indicating that they could be used as CAFs specific markers in various cancer types." (PMID 36744260, 2023). "FAP-IL2v treatment did not alter the number of CD4+ T cells in tumors compared with the vehicle-treated group, but there was higher increase of CD4+ T cells in the tumor on day 7 compared to Day 5, which is consistent with the findings of the tracer." (PMID 35874707, 2022). "The FAP-α specific BIVA probe M1 were well depicted the tumor margin and interstitial space, which concentrated the signal in tumor for better bioimaging, but the M2 has no obvious Congo Red, which means there was no assembly inside tumor." (PMID 35058435, 2022). "Gunderson and colleagues obtained similar results in a PDAC model, but, at the same time, the authors reported that FAP+ CAF targeting combined with ionizing therapy, while enabling anti-tumor T-cell infiltration and function, did not result in sufficient tumor clearance to extend animal survival." (PMID 35892828, 2022). "However, FAPI-04 and FAPI-46 are indeed characterized by longer tumor retention time 1 h p.i., compared with FAPI-02, yet this aspect is solely relevant for FAP-targeted radionuclide therapy and hence not of essence in this analysis." (PMID 34050777, 2021). "FAP intensity, but not CD8a density, acted as an independent prognostic marker in multivariable analyses also, including CD8a density, age, stage, MMR status, adjuvant treatment, location, tumor differentiation and gender." (PMID 33153037, 2020). "This previous study demonstrated that, in tumors displaying epidermal growth factor receptor (EGFR) amplification, the FAP+ perivascular population lacked EGFR amplification, thereby identifying them as a stromal cell type rather than a subtype of tumor cells residing in the perivascular niche." (PMID 33082953, 2020). "However, when the NF were co-cultured with tumor cells, these co-cultured spheroids showed altered level of α-SMA and FAP but not FSP-1." (PMID 32256977, 2020).
tumor (continued). "Interestingly, not all TAMs in WT 4T1 tumours had detectable HO-1, however this might be explained by differences in the differentiation state of these cells, as both monocytes and TAMs express F4/80, and HO-1 expression correlated with FAP expression in the TAM population." (PMID 30054470, 2018). "Similarly, the sum of score change in stromal markers (α-SMA and FAP) showed a significant difference between HCCs with preoperative TACE and those without (P = 0.047), suggesting an altered tumor stroma after TACE." (PMID 29245907, 2017). "In addition, we corroborated previous findings that tumor cell–derived signals could suppress MHCII antigen presentation, which can also account for the absence of FAP+ apCAFs detected in vivo." (PMID 40215177, 2025). "Moreover, FAP expression positively correlated with immune infiltration, particularly CD4+ T cells, macrophages, and CAFs, while showing a negative correlation with tumor purity." (PMID 41244835, 2025). "We observed a negative correlation between FAP expression and the B-cell transcription factor PAX5 in DLBCL, which further supports the notion that FAP may be regulated by factors related to B-cell differentiation and tumor phenotype." (PMID 41373408, 2025). "Consistently, single-cell RNA-seq analysis of nonmalignant tumor tissues and HGOSC tissues was utilized to investigate the distribution of SFRP2 in TME and a novel subset with the highest enrichment of SFRP2 and CAF markers (COL6A1, COL6A2, FAP) was identified." (PMID 38069266, 2023). "The monoclonal antibody targeting FAP (sibrutuzumab) and the small molecule inhibitors of FAP (F19 and PT100) were well‐tolerated, but no obvious clinical anti‐tumor effect was observed in Phase I clinical trials, and subsequent structural adjustments may be needed." (PMID 34977870, 2021). "[177Lu]Lu-FAPI-02 biodistribution studies showed the highest uptake at 2 h after administration in human FAP-transfected HT-1080 tumor-bearing mice; however, the retention time of [177Lu]Lu-FAPI-02 in the tumor was relatively short and might not be enough to achieve a therapeutic response." (PMID 34681246, 2021). "Through enzymatic and non-enzymatic activities, FAP demonstrates pro-tumorigenic activity involved in migration, invasion, and proliferation of stromal fibroblasts, immune, endothelial, and cancer cells, resulting in ECM degradation, tumor angiogenesis, invasiveness, and immunosurveillance evasion." (PMID 34681246, 2021). "However, in culture, we observe moderate expression of FAP in fibroblasts from both tissue types, suggesting that in culture, the fibroblasts are maintained in an activated state, although potentially not as strongly activated as those found in the NSCLC tumour microenvironment." (PMID 40640541, 2025). "Importantly, dual sequential treatment with FAP-CAR T cells overcomes the negative effects of the TME on Meso-CAR T cells or immune checkpoint blockade in pre-clinical PDAC models, resulting in significant inhibition of tumor growth in multiple PDAC models by anti-PD-1 and by Meso-CAR T cells." (PMID 37607999, 2023).
cancer (942 papers, 2006 to 2026). A tumor composed of atypical neoplastic, often pleomorphic cells that invade other tissues. "Its overexpression across multiple cancer types – particularly within the stroma – has established FAP as a hallmark of cancer‐associated fibroblasts (CAFs)." (PMID 41410015, 2026). "Background/Objectives: Fibroblast activation protein (FAP) has emerged as a promising target for oncologic molecular imaging due to its high expression in cancer-associated fibroblasts and low presence in healthy tissues." (PMID 42075850, 2026). "Background/Objectives: Fibroblast activation protein (FAP), which is abundantly expressed in cancer-associated fibroblasts (CAFs) across various epithelial malignancies, has emerged as a promising target for molecular imaging and radionuclide therapy." (PMID 41599688, 2026). "CONCLUSION: [68Ga]BED003-PET demonstrated consistently high uptake across diverse solid malignancies, supporting its potential role as a tool for multi-cancer diagnostic imaging and patient selection for FAP-targeted radioligand therapy." (PMID 41854769, 2026). "In epithelial tumors, FAP is typically expressed by cancer-associated fibroblasts (CAFs), a heterogeneous population of stromal cells characterized by markers such as FAP, α-smooth muscle actin (SMA), and vimentin." (PMID 40694103, 2026). "We validated stromal FAP as a robust prognostic marker consistently associated with adverse clinical outcomes, including earlier biochemical recurrence, metastasis, and cancer‐specific death." (PMID 41410015, 2026). "Fibroblast activation protein (FAP), widely expressed by cancer-associated fibroblasts (CAFs), emerges as a promising yet underexploited target for drug delivery." (PMID 41695493, 2026). "But more importantly, low levels of FAP were found in healthy tissues, whereas it is overexpressed by CAFs (cancer associated fibroblasts) in more than 90% of epithelial tumors, including breast, lung, pancreas, brain and colon cancer." (PMID 40762892, 2025). "Fibroblast activation protein (FAP) is a serine protease selectively expressed in cancer-associated fibroblasts (CAFs), fibrotic tissues, and areas of active tissue remodeling, making it an attractive target for diagnostic imaging across a spectrum of disease." (PMID 40283957, 2025). "Fibroblast activation protein (FAP) is overexpressed in cancer-associated fibroblasts with minimal expression in normal tissues." (PMID 41301015, 2025). "Further studies are warranted to elucidate the mechanisms underlying reduced FAP concentrations in cancer patients and assess its potential as a biomarker." (PMID 40690098, 2025). "As a canonical marker for an activated fibroblast, FAP is highly expressed in not only fibrotic tissue, but also the stroma of many types of solid tumour, predominantly by cancer-associated fibroblasts (CAFs) that support the tumour." (PMID 40293537, 2025). "FAP is expressed by cancer-associated fibroblasts but also by activated cardiac fibroblasts early after acute MI in patients." (PMID 39744226, 2025). "These include combining FAP inhibitors with immunotherapy and developing FAP-targeted CAR-T cells to target cancer-associated fibroblasts." (PMID 40741380, 2025). "Single-cell atlases in CRC further resolve functionally distinct myeloid states; for example, SPP1high macrophages that interact with fibroblast activation protein (FAP)+ cancer-associated fibroblasts and align with desmoplastic, T-cell–excluded niches." (PMID 41567197, 2025). "Fibroblast activation protein (FAP) is highly overexpressed on the membrane of cancer-associated fibroblasts (CAFs) in approximately 90% of epithelial-derived tumors." (PMID 40283957, 2025). "Cancer-associated fibroblasts are a promising target, leading to the development of FAP-targeted CAR-T cells." (PMID 40417720, 2025). "FAP is a type II membrane-bound glycoprotein, and its expression is associated with poor prognosis in several types of cancer." (PMID 41345810, 2025).
cancer (continued). "The cancer-associated fibroblast (CAF)-enriched subtype showed elevated FAP and Vimentin expression, abundant CAFs, high proliferative activity, and poor prognosis." (PMID 40670349, 2025). "Fibroblast activation protein (FAP) is a type II transmembrane serine protease predominantly expressed by cancer-associated fibroblasts (CAFs) in more than 90% of epithelial malignancies." (PMID 41425958, 2025). "The imaging efficacy of FAP‐targeted imaging is closely linked to the abundance of FAP in specific cancers." (PMID 40656546, 2025). "Elevated FAP expression is associated with poor prognosis across several cancer types, including carcinomas, sarcomas, and other solid tumors." (PMID 41373408, 2025). "Fibroblast activation protein (FAP) is a transmembrane glycoprotein that is overexpressed on cancer-associated fibroblasts of epithelial malignancies." (PMID 40473461, 2025). "FAP is expressed by a TGFβ-driven mechanism in cardiac fibroblasts and cancer associated fibroblasts, promoting fibroblast migration and exerting gelatinolytic activity in vitro." (PMID 40690098, 2025). "In the earlier studies, FAP was reported to be a promising pan-cancer diagnostic and therapeutic target." (PMID 40457405, 2025). "FAP is selective for cancer-associated fibroblasts in tumors and myCAFs display the largest fibroblast population." (PMID 40523922, 2025). "In most epithelial carcinomas, FAP is primarily overexpressed in stromal cancer-associated fibroblasts (CAFs)." (PMID 40607439, 2025). "Multiplex immunofluorescence for FAP and αSMA, two markers for cancer-associated fibroblasts, showed that the relative abundance of C5aR1+FAP+ cells and C5aR1+SMA+ cells was higher in cSCCs than in normal skin, AK, and cSCCIS." (PMID 40056975, 2025). "[177Lu]Lu-FAPI, a novel radioligand targeting FAP abundantly expressed in cancer-associated fibroblasts, has rapidly emerged as a promising theranostic agent for solid tumors with limited treatment options." (PMID 40964544, 2025). "The results revealed a significant overlap between LINC01711 and FAP expression, indicating that LINC01711 is predominantly expressed in FAP-positive cancer-associated fibroblasts (CAFs)." (PMID 40855046, 2025). "The effective scores of CD8+ T cells, PD-1+CD8+ T cells, FOXP3+CD4+ T cells and FAP+ cells, which represents cancer-associated fibroblasts (CAFs), were higher in the DCB than those in the NDB." (PMID 40082418, 2025). "FAP is primarily overexpressed in cancer-associated fibroblasts, which are integral to the tumour microenvironment and play a key role in cancer aggressiveness and progression." (PMID 40278857, 2025). "Studies have shown that fibroblast activation protein (FAP), a derivative of cancer-associated fibroblast-like cells (CAFLCs), can activate the JAK2/STAT3 signaling pathway in GC." (PMID 40485724, 2025). "FAP staining via immunohistochemistry in lung metastases indicated higher levels of cancer-associated fibroblasts (CAFs) in the CAF2 and CAF3 groups." (PMID 40280913, 2025). "Fibroblast activation protein (FAP) is overexpressed by cancer-associated fibroblasts in the microenvironment of various epithelial and mesenchymal malignancies, making them distinct from normal fibroblasts." (PMID 40647503, 2025). "Fibroblast activation protein (FAP) is a serine protease, overexpressed in various cancers, which has been explored as a diagnostic and therapeutic target." (PMID 40126602, 2025). "This enhanced detection rate is attributed to FAPI's selective targeting of fibroblast activation protein (FAP), which is overexpressed in cancer-associated fibroblasts within the tumor microenvironment, and is considered a marker for pro-tumorigenic stroma." (PMID 40417720, 2025). "Fibroblast activation protein (FAP) is an antigen expressed on cancer associated fibroblasts as part of the tumor microenvironment and on the surface of cancer cells in a variety of malignant neoplasms." (PMID 40022163, 2025).
cancer (continued). "Fibroblast-activation protein (FAP) is predominantly expressed in cancer-associated fibroblasts, which are found in the stroma of 80–90% of all cancers." (PMID 39857102, 2025). "These include strategies to target cancer cells specifically and a pan-cancer approach by targeting fibroblast-activated protein (FAP) upregulated on cancer-associated fibroblasts (CAF)." (PMID 41049848, 2025). "Fibroblast activation protein (FAP) is a type II transmembrane serine protease that is overexpressed in cancer-associated fibroblasts (CAFs) found in most epithelial tumors." (PMID 41301015, 2025). "An elevated FAP expression is associated with a poor prognosis and adverse treatment outcomes across various cancers." (PMID 40283957, 2025). "The development of this tracer is significant as FAP is overexpressed in numerous epithelial carcinomas, making it an attractive target for both diagnostic and therapeutic applications." (PMID 40006089, 2025). "Fibroblast activation protein (FAP) has been found to be overexpressed in cancer-associated fibroblasts of multiple cancer types." (PMID 38740576, 2024). "FAP, a glycoprotein of the dipeptidyl peptidase family, is abundantly expressed in cancer-associated fibroblasts (CAFs) of numerous epithelial tumors (e.g., sarcoma and mesothelioma)." (PMID 39898278, 2024). "FAP is a membrane-bound protein, overexpressed in cancer-associated fibroblasts (CAFs), and found in 90% of epithelial cancers." (PMID 39266288, 2024). "Among all these possible candidate markers, FAP, is predominantly enriched in cancer-associated fibroblasts." (PMID 39034310, 2024). "Fibroblast activation protein (FAP) is a membrane protease that is highly expressed on the surface of cancer-associated fibroblasts." (PMID 38176719, 2024). "Fibroblast activation protein (FAP) is a membrane protein expressed on cancer-associated fibroblasts (CAFs) that plays an essential role in TNBC proliferation, migration, and invasion." (PMID 39519118, 2024). "Regarding chemotherapy resistance, the introduction of FAP into ovarian tumor cells has been associated with reduced sensitivity to cisplatin, a first-line cytotoxic agent for this cancer." (PMID 39765634, 2024). "Fibroblast activating protein (FAP) is a cell surface marker of cancer-associated fibroblasts with a distinct pro-tumorigenic role." (PMID 39579201, 2024). "The fibroblast activation protein (FAP) is a cell membrane protein overexpressed in cancer-associated fibroblasts, representing a component of the tumor stroma." (PMID 38786341, 2024). "FAP is a characteristic marker of mesenchymal cells, such as cancer‐associated fibroblasts and pericytes, in many types of malignancies." (PMID 38705944, 2024). "Fibroblast activation protein (FAP) is a surface glycoprotein expressed by CAFs and has been implicated in multiple cancer types." (PMID 38826849, 2024). "The [68Ga]Ga-FAPI PET imaging target is fibroblast activation protein (FAP) which is commonly overexpressed in cancer-associated fibroblasts within the tumor microenvironment of various cancers, including glioblastoma." (PMID 39162901, 2024). "Cancer-associated fibroblasts (CAFs) are upregulated in many cancers and activate fibroblasts from the stroma via fibroblast activation protein (FAP)." (PMID 38256250, 2024). "There is however a fundamental difference in the underlying biochemistry because αvβ6-integrin is expressed by the cancer cells, whereas FAP is expressed by cancer-associated fibroblasts (CAFs), and thus its presence is essentially restricted to the stroma." (PMID 39618940, 2024). "It is also necessary to develop panels containing MDSCs markers as well as other markers like CD19 (B cells), Granzyme B (activated T cells), Foxp3 (regulatory T cells), α-SMA (cancer associated fibroblasts, CAFs) and FAP (CAFs) to characterize the TME." (PMID 38877529, 2024).